CLDN6 (claudin 6)
Diseases named in the same sentence as CLDN6 in open-access papers (continued):
Sharing a sentence is not in itself a finding about the gene and the disease.
tumor (continued). "Cohorts treated with MVvac2-CLDN6 or MVvac2-gag-CLDN6 experienced an even stronger delay in tumor growth and a further increase of median survival (11 vs. 9 days post initiation of treatment)." (PMID 29203786, 2017). "5-aza-dC up-regulated CLDN6 expression and suppressed migration and invasion in MCF-7 cells, whereas CLDN6 silence restored tumor malignance in MCF-7 cells." (PMID 27461117, 2016). "Xu found that claudin-6 is an important factor influencing lymphatic metastasis, whereas up-regulation of HDAC1 is associated with tumor progression and invasiveness in breast IDC." (PMID 23276146, 2012). "Our data suggests that down-regulation of claudin-6 is an important factor influencing lymphatic metastasis; whereas up-regulation of HDAC1 is associated with tumor progression and invasiveness in breast IDC." (PMID 22455563, 2012). "High CLDN6 expression was defined as moderate-to-strong membranous staining in ≥50% of tumor cells." (PMID 42072801, 2026). "CLDN6 has been reported to be upregulated in most malignancies, including lung adenocarcinoma and squamous carcinoma, and acts as a pro-oncogene, promoting tumor migration and invasion." (PMID 40687428, 2025). "However, a dual role of CLDN6 in tumor progression has also been discussed, and functional studies addressing the role of CLDN6 in pediatric tumors should be performed in the future." (PMID 40149257, 2025). "CLDN6 caused an increase in mitochondrial membrane density and lipid droplet, and a decrease in mitochondrial cristae, which were aggravated after treatment with sorafenib as observed by TEM in xenograft tumor tissue." (PMID 39984471, 2025). "Therefore, targeting CLDN6 will presumably contribute to eliminating less differentiated and more aggressive tumor cells." (PMID 40149257, 2025). "While the exact molecular mechanisms remain to be fully elucidated, CLDN6 may influence tumor progression by disrupting tight junction integrity, altering ionic homeostasis at the lateral membrane, and modulating the EMT." (PMID 41211166, 2025). "In that small cohort of patients (n = 21), all responding patients had tumors with >80% of tumor cells expressing 2+/3+ CLDN6 at prescreening, suggesting that the CLDN6 expression level may be predictive of the outcome." (PMID 40149257, 2025). "To establish whether engineered human B cells can take up antigen from the membrane of tumor cells, we labeled the membranes of CLDN6-expressing tumor cell lines (PA-1, OVCAR3, and OV90) and a CLDN6-negative tumor line (A549) with a membrane intercalating dye." (PMID 40808959, 2025). "High CLDN6 expression correlates with poor prognosis and may drive tumor proliferation and migration, making it an attractive therapeutic target for antibody-based strategies." (PMID 41211166, 2025). "PBM of CLDN6 is an important structure to exert signal transduction in tumor progression." (PMID 39984471, 2025). "A similar tumor promoter effect of CLDN6 was demonstrated in human hepatocellular carcinoma (hHCC)." (PMID 38731853, 2024). "Interestingly, 93.8% of patients were CLDN6 positive, as assessed by IHC staining of archival tumor tissues." (PMID 38371623, 2024). "Previously, we confirmed the role of CLDN6 as a tumor suppressor of BC for the first time." (PMID 39169280, 2024). "Additionally, the analyses of small-scale tissue microarrays can obscure the heterogeneity of CLDN6 expression in large tumor samples." (PMID 37592303, 2023). "All responding patients had tumors with >80% of tumor cells expressing 2+/3+ CLDN6 at prescreening, suggesting that CLDN6 expression level may be predictive of outcome." (PMID 37872225, 2023). "They demonstrated that CLDN6 attenuates hypoxia-induced tumor metastasis via SUMOylation and they speculated that these findings might provide a novel strategy to treat BC and a mechanism to be exploited in anti-cancer therapy." (PMID 35465332, 2022).
tumor (continued). "Claudin 6 (CLDN6) appears to be able to regulate the HIF-1α pathway through SENP1 in BC cells and BC patients with primary CLDN6 loss are more prone to have tumor metastasis, due to a lack of feedback mechanism that impairs HIF-1α stability." (PMID 35465332, 2022). "In addition, GEN1046 significantly enhanced CLDN6-TCR+ T-cell–mediated cytotoxicity of MDA-MB-231 tumor cells more efficiently than atezolizumab or combinations of monovalent bsAb controls." (PMID 35176764, 2022). "Reactivation of CLDN6 is often observed in LIHC tumor tissues and precancerous lesions." (PMID 36482887, 2022). "The finding reveals that CLDN6 serves as a cancer-promoting gene in the majority of malignant tumors and might be involved in tumor formation or cancer development." (PMID 34409042, 2021). "Of course, altered metabolic pathways upon CLDN6 overexpression such as purine, pyrimidine, and fatty acid biosynthesis metabolism may also contribute to the inhibitory effect of CLDN6 on tumor growth, which is our ongoing research." (PMID 35008557, 2021). "Furthermore, as a member of the claudin family, the function of CLDN6 varies among different types of tumours." (PMID 32093760, 2020). "In conclusion, these data show that prophylactic vaccination with MVvac2-gag-CLDN6 strongly inhibits and can even protect mice against highly aggressive B16-mCLDN6/hCD46 cells forming lung metastasis after i.v. application of tumor cells mimicking pulmonary spread via the hematogenous route." (PMID 29203786, 2017). "Therapy proved most effective when directed against truly tumor-specific antigens such as EGFRvIII or CLDN6, or when CAR-T cell activation could be selectively triggered by cancer cells exhibiting higher expression levels of tumor-associated antigens like CLDN18.2 or GD-2 compared to normal tissues." (PMID 41154636, 2025). "Particularly high-risk WTs are characterized by blastemal tumor cells, which are CLDN6-negative." (PMID 40149257, 2025). "In addition, several studies have analyzed the relationship between CLDN6 and tumor prognosis." (PMID 34948213, 2021). "The research team confirmed the anti-tumor activity of this ADC both as a monotherapy and in conjunction with sorafenib by integrating an anti-CLDN6 monoclonal antibody with the cytotoxic drug DM1 (CLDN6-DM1)." (PMID 40362316, 2025). "[89Zr]Zr-DFO-IMAB027 showed high contrast when visualizing CLDN6-expressing xenografts for PET imaging, and [177Lu]Lu-DOTA-IMAB027 induced rapid tumor regression in a preclinical model of EC." (PMID 39915118, 2025). "Tumor volume and weight were significantly reduced in the MDA-MB-231/CLDN6+ADM group compared to the MDA-MB-231/CLDN6+control group, whereas no significant changes were observed in the MDA-MB-231/CLDN6+CQ group." (PMID 40959289, 2025). "Preclinical studies in mice revealed a marked increase in proliferating CLDN6-CAR-T cells following treatment with CAR-CLDN6 and subsequent administration of CLDN6-LPX, resulting in complete tumor regression within 14 days." (PMID 40382583, 2025). "Tumor volume and weight in the MDA-MB-231/CLDN6+CQ+ADM group were significantly smaller than those in the MDA-MB-231/CLDN6+ADM or MDA-MB-231/CLDN6+CQ group." (PMID 40959289, 2025). "Compared with the MDA-MB-231/Vec+ADM group, the tumor volume and weight were higher in the MDA-MB-231/CLDN6+ADM group." (PMID 40959289, 2025). "IHC staining and WB in xenograft tumor tissues revealed lower NRF2 and GPX4 expressions in the CLDN6 overexpression and sorafenib-treated CLDN6 overexpression groups compared to controls." (PMID 39984471, 2025). "The use of in vitro and in vivo models has demonstrated that targeting CLDN1, CLDN3, CLDN4, CLDN6 and CLDN18.2 consistently reduces tumor burden across a multitude of different cancer types, with specific intra-tumoral accumulation and low rates of AEs." (PMID 38371623, 2024).
tumor (continued). "Among annotations of differentially enriched regions, we discovered that tumor suppressor genes such as LHPP, VGLL4, USP53, and CLDN6 had increased H3K9ac signals in their promoter regions under the metformin condition." (PMID 38831454, 2024). "Next, we evaluated the expression of CLDN6, WIP and LC3 in tumor samples by IHC of the tissue microarray." (PMID 36935496, 2023). "Excessive CLDN6/SFK signaling stimulated cell proliferation and migration, as well as tumor growth and invasion into fibrous capsules in xenografts." (PMID 37443730, 2023). "Autologous CLDN6-CAR-NK cells were engineered to express CCL19/IL7 and scFv targeting PD-1/CTLA-4/Lag-3 to increase the anti-tumor efficacy against CLDN6-positive solid tumors." (PMID 37371075, 2023). "Significant differences in CLDN3, CLDN4, CLDN5, CLDN6, CLDN9, CLDN11, and CLDN12 expression were evident as a function of tumor stage." (PMID 35281827, 2022). "In a repetitive in vitro killing assay, CLDN6- or CLDN18.2-TCAR and CAR-BBζ T cells were challenged three times at 5- to 7-day intervals with tumor spheroids derived from CLDN6+ or CLDN18+ PA-1 cells." (PMID 36923303, 2022). "The present study combined and analyzed the prognostic potential of CLDN6 and CLDN10 with the tumor immune microenvironment." (PMID 34249076, 2021). "As described, the TAA Claudin-6 (CLDN6), a typical four-transmembrane protein, was chosen for pre-clinical proof of concept, as CLDN6 fulfills all criteria for an ideal tumor vaccination antigen." (PMID 29203786, 2017). "Tumor and non-tumor samples differed significantly in the expression of 10/22 genes: CCNB1, CLDN4, CLDN6, MMP2, MUC1 (all: p < 0.05), BAG1, SERPINB3 (all: p < 0.01), CD44 (standard variant), MKI67, and MYBL2 (all: p < 0.001)." (PMID 27542596, 2016). "Another sample was CLDN6 negative, and another sample showed CLDN6 positivity only in a part of the tumor epithelium, while the blastemal component was completely CLDN6-negative." (PMID 40149257, 2025). "Our results show that qRT–PCR data correlate well with IHC data if the tumor is CLDN6-negative or CLDN6 expression is homogeneous." (PMID 40149257, 2025). "Based on the promising results achieved thus far with CLDN6 and CLD18.2, there will be continued interest in exploring additional claudin family members that are emerging as important targets in different stages of tumor growth and metastatic progression." (PMID 38371623, 2024). "Additionally, CLDN6 and CLDN18 have been proposed as targets for tumor inhibition in proof-of-concept studies." (PMID 38540693, 2024). "In order to enlarge the dataset, various tumor cell lines and primary AML patient samples expressing the selected genes were additionally included, some of these cell lines were transduced with CTCFL, CLDN6 and/or HLA class I molecules." (PMID 37026005, 2023). "One of the key findings of our interim analysis of first-in-human data was the manageable AE profile, with a lack of on-target/off-tumor toxicity attributable to cognate CLDN6 CAR-T cell activity at the tested DLs." (PMID 37872225, 2023). "The CARVac strategy demonstrated that LNP-mediated delivery of the CLDN6 antigen to antigen-presenting cells (APCs) in the lymphoid compartments of mice could promote robust expansion of CLDN6 CAR-T cells and improved anti-tumor efficacy." (PMID 38090585, 2023). "We did not observe any interdependencies between CLDN6 expression and tumor stage (pT), lymph node stage (pN), lymph vessel, blood vessel, and perineural invasion or the application of neoadjuvant treatment." (PMID 37592303, 2023). "Due to its exclusive expression in several solid tumors, CLDN6 may be a promising target, for example, for CAR T-cell therapy and other patient- and tumor-individualized approaches in these cancers of high medical need." (PMID 37592303, 2023). "In addition, the protein expression of CLDN6, WIP and LC3 in the lung metastatic tumor tissues was tested by IHC." (PMID 36935496, 2023).
tumor (continued). "We did not observe any correlation between dichotomized CLDN6 expression and tumor stage (pT), lymph node stage (pN), metastasis stage (pM), age, and sex (data not shown)." (PMID 37592303, 2023). "For PFI, the higher expression of CLDN6 had a worse PFI in subgroup of weight > 80, subgroup of BMI > 30, subgroup of postmenopause, subgroup of primary therapy outcome (CR), subgroup of residual tumor (R0), and subgroup of clinical stage III." (PMID 34409042, 2021). "Given the important role in tumors and its low or no expression in normal tissues, CLDN6 is an ideal target for tumor therapy." (PMID 34948213, 2021). "Meanwhile, through analysis, we found for the first time that the high expression of CLDN6 in hHCC tissues was related to the degree of tumor differentiation, but not related to tumor stage, lymph node metastasis, gender or age of patients." (PMID 34405008, 2021). "For DSS, the higher expression of CLDN6 had a worse DSS in subgroup of age > 60, subgroup of weight > 80, subgroup of BMI > 30, subgroup of tumor invasion ≥ 50%, subgroup of postmenopause, subgroup of primary therapy outcome (CR), and subgroup of radiation therapy (No)." (PMID 34409042, 2021). "In summary, the up-regulation of claudin-6 may result in abnormal structure and function of TJs and activation of MMP-2 both of which can result in some of the highly invasive tumor cells acquiring invasive and metastatic phenotype." (PMID 24245968, 2013). "Claudin-6 expression was found to be independent of the tumor subtype but was inversely correlated with lymph node metastasis." (PMID 22455563, 2012). "The comparison revealed that the expression of CLDN6 in the same tumor may not be identical or even contradictory in different studies." (PMID 34948213, 2021). "As expected, the tumor sample population showed higher expression levels of pro-mitotic genes such as CCNB1 and MYBL2, genes that modulate the host immune response, such as SERPINB3, and the tight-junctions proteins claudin-4 and claudin-6, which are often deregulated in cancers." (PMID 27542596, 2016). "Furthermore, claudin 6 (CLDN6) is a cell surface member protein expressed on multiple solid tumor tissues and its expression levels differ by tumor types while the expression is not observed on normal adult tissue." (PMID 36497465, 2022).
cancer (76 papers, 2012 to 2026). A tumor composed of atypical neoplastic, often pleomorphic cells that invade other tissues. "The altered expression of CLDN6 was linked to the development of various cancers whose malignant phenotypes include proliferation and apoptosis, migration and invasion and drug resistance." (PMID 36362009, 2022). "Strong evidence indicates that the altered expression of CLDN6 is linked to the development of various cancers." (PMID 34948213, 2021). "Differential gene expression analysis showed overexpression of classic epithelial genes (for example, SFTPC and STEAP1), genes associated with cancer (for example, CLDN6) and regulators of EMT (for example, VIM, FN 1 and CDH2) in Oncopig LC versus normal pig lung tissues." (PMID 41407936, 2026). "Differential gene expression analysis showed overexpression of classic epithelial genes (e.g., SFTPC and STEAP1), genes associated with cancer (e.g., CLDN6), and regulators of EMT (e.g., vimentin, fibronectin 1, and N-cadherin) in Oncopig LC versus normal pig lung tissues." (PMID 39975891, 2025). "This implies or suggests that CLDN6 may have potential as a diagnostic marker or even a therapeutic target in these cancer types." (PMID 38731853, 2024). "However, it was confirmed that the variety of CLDN6 expression was associated with the occurrence of cancers." (PMID 36362009, 2022). "The ROC curve was performed to assess the diagnostic value of CLDN6 in pan-cancer." (PMID 34409042, 2021). "Taken together, CLDN6 may be a remarkable molecular biomarker for diagnosis and prognosis in pan-cancer and an independent prognostic risk factor of UCEC, presenting to be a promising molecular target for cancer therapy." (PMID 34409042, 2021). "In addition, there are meaningful associations between CLDN6 expression level and molecular subtypes of seven cancer types, including UCEC, BRCA, ESCA, LUSC, HNSC, OV, and STAD." (PMID 34409042, 2021). "Besides, high accuracy in predicting cancers and notable correlations with prognosis of certain cancers suggest that CLDN6 might be a potential diagnostic and prognostic biomarker of cancers." (PMID 34409042, 2021). "Cldn6 may also be implicated in the development of diverse cancers." (PMID 27763528, 2016). "Whereas CLDN6 is considered an attractive target for cancer therapy due to its cancer specificity, its biology remains poorly understood." (PMID 41628300, 2026). "The expression profiles of claudins differ across various cancer types, with CLDN6 undergoing extensive investigation through pan-cancer analyses." (PMID 41399659, 2026). "Claudin-6 was notably upregulated in 20 different cancers; however, its expression was significantly reduced in GBM tissues, chromophobe renal cell carcinoma (KICH), acute myeloid leukemia (LAML), clear cell renal cell carcinoma (KIRC and LGG)." (PMID 41399659, 2026). "In CLDN6-positive samples, CLDN6 was generally expressed with 2+ or 3+ intensity in substantial proportions of the cancer cells." (PMID 41073135, 2025). "Currently, one clinical trial has reported results regarding the efficacy of targeting CLDN6 in cancer (NCT03760081)." (PMID 38371623, 2024). "CLDN6 is involved in regulating the proliferation and apoptosis of cancer cells through different pathways, leading to the procancer or anticancer effects of CLDN6 in different cancers." (PMID 38481806, 2024). "In the TNBC cell line, CLDN6 promotes adriamycin-resistant cancer clones via the afadin (AF-6)/ERK pathway." (PMID 38731853, 2024). "Other claudin family members besides CLDN1, CLDN3, CLDN4, CLDN6 and CLDN18.2 have also been implicated in various stages of cancer progression, including metastasis." (PMID 38371623, 2024). "CLDN6-23-ADC demonstrated dose-dependent in vitro growth inhibition in ARK2 and OVCA429 CLDN6-expressing cancer cells." (PMID 38371623, 2024).